CBR1 (carbonyl reductase 1)
Diseases named in the same sentence as CBR1 in open-access papers (continued):
Sharing a sentence is not in itself a finding about the gene and the disease.
tumor (17 papers, 2007 to 2025). "EGCG enhances anti-tumor activity by inhibiting the activity of carbonyl reductase 1 (CBR1) and P-gp in the liver cells." (PMID 39725830, 2024). "Women with high CBR1 tumour expressions were slightly more likely to have positive lymph nodes, stage III and IV disease, HER2 positive status and to have received adjuvant chemotherapy, hormone therapy and trastuzumab therapy." (PMID 34575629, 2021). "CBR1 immunoreactivity was observed in the cytoplasm and was heterogeneous within and between evaluated tumours." (PMID 34575629, 2021). "Another important role of CBR1 is to regulate tumor progression, including growth, proliferation, invasion, and metastasis." (PMID 31942176, 2020). "Subsequently colony formation assays and xenograft tumor mouse model was used to verify the relationship between CBR1 expression and radiosensitivity in HNSCC cells." (PMID 30376862, 2018). "Downstream genes of Nrf2, such as CBR1, can be effective targets to regulate intracellular ROS levels in diverse tumours including HNSCC." (PMID 30376862, 2018). "Our results showed that the combination of CBR1 inhibition and IR reduced colony formation in vitro and suppressed tumour growth in vivo in xenograft models." (PMID 30376862, 2018). "The result showed that the combination of CBR1 inhibition and IR significantly suppressed tumour growth compared with vehicle, only radiation, or only CBR1 inhibition." (PMID 30376862, 2018). "Protein levels of AKR1C1, AKR7A3, and CBR1 significantly correlated with the respective transcript levels assessed by qPCR in the same tumor samples (Spearman ρ = 0.47, P = 0.003, Spearman ρ = 0.61, P < 0.001, and Spearman ρ = 0.44, P = 0.007, respectively)." (PMID 25526449, 2014). "Expression of AKR1C1, AKR1C2, AKR7A3, CYP3A4, and CBR1 was assessed by immunoblotting in protein lysates from tumor tissue samples of the independent pretreatment set of patients." (PMID 25526449, 2014). "Other similarities have been observed where CBR1 expression was positively correlated with Gleason score (rs = 0.21, p < 0.001), tumour stage (rs = 0.11, p < 0.05), percentage of the specimen that contains tumours (rs = 0.17, p = 0.01) and EGFR (rs = 0.18, p = 0.01)." (PMID 34575629, 2021). "To explore whether CBR1 participates in tumor cell proliferation, we downregulated CBR1 expression in HNSCC cells by transfection with specific siRNAs." (PMID 31942176, 2020). "Moreover, the combination of CBR1 depletion with IR dramatically inhibited primary tumour growth in a xenograft tumor mouse model." (PMID 30376862, 2018). "Previous studies have shown that CBR1 and CBR2 are involved in reducing the progression of tumours in animal models and have antitumoral action in vivo, mainly by inducing apoptosis and cell cycle arrest." (PMID 34575629, 2021). "No significant changes in expression of AKR1B1, AKR1D1, AKR7A2, CBR1, CYP2C8, and CYP2C9 between tumor and control tissues were found." (PMID 25526449, 2014). "As for PCA clusters, high Pearson correlation coefficients of gene expression within the cluster were only in case of AKR1C3, CBR1, CBR3 genes (r = 0.64 − 0.77, p-value < 0.05) in LUSC tumor as well as CBR1 and CBR3 (r = 0.72 − 0.86, p-value < 0.05) in ESCA tumor." (PMID 35453789, 2022). "Models of CBR1 and PTGIR post-translational regulation models were mediated via neddylation and ubiquitination/deubiquitination as well as phosphorylation depending on tumor types." (PMID 35453789, 2022). "While CBR1 expression was positively correlated with lymph node metastases and HER2 status, nuclear CBR2 expression was positively correlated with histologic type, ER/PR positive status and negatively correlated with tumour grade." (PMID 34575629, 2021).
metabolic disease (2 papers, 2020 to 2025). A congenital disorder (due to inherited enzyme abnormality) or acquired (due to failure of a metabolically important organ) disorder resulting from an abnormal metabolic process. "Inhibitors of CBR1, particularly flavonoids, exist in many foodstuffs and food supplements and are often advocated as supplements for people with metabolic disease." (PMID 39869501, 2025). "First, because the details of metabolic disorder are extremely complex, the molecular mechanisms of metabolic disorder regulated by 25(OH)D should be examined outside of the role it plays in the Nrf2/CBR1 pathway." (PMID 32184720, 2020).
infection (1 paper, 2022). The state of being infected such as from the introduction of a foreign agent such as serum, vaccine, antigenic substance or organism. "After infection Cbr-1 (2 × 109 CFU/fish) for 12 h and 24 h, 20 surviving crucian carp were injected with phage (1 × 109 PFU/ fish)." (PMID 35601403, 2022).
neurodegenerative disease (1 paper, 2025). A disorder of the central nervous system characterized by gradual and progressive loss of neural tissue and neurologic function. "Reduction in antioxidant glutathione (GSTP1 identified here) may occur in MSA, but peroxiredoxins or CBR1 (both proteins protect from oxidative stress) have not been directly implicated in MSA but have been implicated in other neurodegenerative diseases and neurotoxic insults." (PMID 40122840, 2025).
CBR1 also shares sentences with these, for which no sentence is quoted: glioma (2 papers); Glucose intolerance (2); Hyperglycemia (2); metabolic syndrome (2); schizophrenia (2); acute leukemia (1); bladder disorders (1); cardiovascular disease (1); cervical cancer (1); chorioamnionitis (1); Cognitive impairment (1); dementia (1); end-stage renal disease (1); glioblastoma (1); heart hypertrophy (1); insulinoma (1); mantle cell lymphoma (1); memory impairment (1); mood disorder (1); prostatic neoplasms (1); psychiatric disorder (1); rheumatoid arthritis (1); trisomy 21 (1); viral infection (1); vitiligo (1).